MYCN (MYCN proto-oncogene, bHLH transcription factor)
Diseases named in the same sentence as MYCN in open-access papers (continued):
Sharing a sentence is not in itself a finding about the gene and the disease.
neuroblastoma (continued). "To investigate, we used the CHK1i CCT244747 as it has shown efficacy in a transgenic model of MYCN-driven neuroblastoma." (PMID 36240065, 2022). "Note that non-MYCN–amplified neuroblastoma cells express MYC, albeit at a lower level than MYCN in amplified lines." (PMID 36874405, 2022). "The high cysteine demand of MYCN-amplified childhood neuroblastoma is met by uptake and transsulfuration." (PMID 35484422, 2022). "In a first, our laboratory has shown that, MYCN-amplified neuroblastoma cells secreted exosome-like extracellular vesicles whose cargo contain oncogenic miRNAs." (PMID 36793342, 2022). "As a result, GLDC knockdown markedly inhibits the proliferation and tumorigenicity of MYCN-amplified neuroblastoma cell lines." (PMID 36077650, 2022). "MYCN is a transcription factor whose target genes are widely involved in metabolism, apoptosis, and cell growth, and its dysregulation in neuroblastoma leads to increased proliferation, decreased apoptosis, and differentiation arrest." (PMID 35943801, 2022). "For this reason, HDACs inhibitors are considered a viable route to target MYCN-amplified neuroblastomas." (PMID 36139583, 2022). "Expression levels of E2F1 and E2F3 were higher in neuroblastoma patients with MYCN amplification or age at diagnosis ≥ 18 months." (PMID 35764946, 2022). "We found that MYCN levels and activity have a direct effect on fatty acid amount, as well as on glucose as the preferred carbon source for fatty acid synthesis in neuroblastoma, in agreement with our earlier results and studies in other MYC-driven tumors." (PMID 33659885, 2021). "This homeostasis seems disturbed in neuroblastoma where MYCN upregulation coincides with severely increased expression of the miR-17-92 cluster." (PMID 34026620, 2021). "When immunoprecipitated endogenous MYCN from MYCN-amplified neuroblastoma cells was immunoblotted with a ubiquitin antibody, we found that combination therapy markedly increased MYCN ubiquitination." (PMID 33658627, 2021). "Our investigation of miRNA expression in MNA neuroblastoma indicated that a substantial number of reported or predicted MYCN-regulatory miRNAs are upregulated in MNA." (PMID 34026620, 2021). "There is increased evidence in neuroblastomas that these two signaling cascades (i.e., MYCN and PI3K) interact, which contributes to the poorer prognosis." (PMID 34539578, 2021). "Similar results were obtained in vivo in the immunocompetent transgenic neuroblastoma mouse model Th-MYCN, which closely recapitulates the main features of poor outcome human neuroblastoma, as well as immunocompromised mouse model." (PMID 34440056, 2021). "Here, we have also provided data linking high expression of H2A.Z.1 to MYCN as bad prognostic feature in Neuroblastoma." (PMID 34423893, 2021). "A clinical inhibitor of Cdk9 and Cdk2, CYC065, can hinder the transcriptional activation of N-Myc by inhibiting the Cdk9 in P-TEFb complex, realizing the therapeutic effect on MYCN-amplified neuroblastoma." (PMID 34658888, 2021). "Next, we determined the combination of age and MYCN amplification in the predication of the clinical outcomes of pediatric neuroblastoma." (PMID 34116676, 2021). "It has been shown that inhibiting PI3K/AKT/mTOR signaling cascade induces downregulation of MycN expression and reduces the growth of neuroblastoma cells in vitro and in vivo." (PMID 33390782, 2021). "Further studies revealed that the transferrin receptor 1 was upregulated in response to such MYCN amplification, leading to increased GPx4 sensitivity and rendering neuroblastoma cells vulnerable to ferroptosis induction." (PMID 34926298, 2021). "Alterations in copy number or changes in expression of MYCN has also been reported in other cancers such as neuroblastoma, medulloblastoma, glioblastoma multiforme, Rhabdomyosarcoma and pancreatic tumors." (PMID 34680394, 2021).
neuroblastoma (continued). "Treatment with ATRA has been reported to down-regulate the expression of MYCN and induce cell cycle arrest with either differentiation or apoptosis in MYCN-amplified neuroblastoma cells." (PMID 34669465, 2021). "These tumors exhibited a RNA expression signature similar to that of ALK mutant/MYCN driven neuroblastoma." (PMID 34885007, 2021). "The 10-year EFS and OS of 47% and 56%, respectively, in the study group is well in line with other reports on localized neuroblastoma with MYCN amplification." (PMID 34503173, 2021). "Modulation of MYCN expression also increases the sensitivity of neuroblastoma cells to other drugs such as vincristine and doxorubicin." (PMID 34832966, 2021). "The adrenergic CRC consists of an interdependent autoregulatory network that includes HAND2, ISL1, PHOX2B, GATA3, ASCL1, and TBX2 and is essential to drive the expression of MYCN and to facilitate the growth and survival of MYCN-amplified neuroblastoma cells." (PMID 34669465, 2021). "Loss of caspase-2 inconsistently delayed tumorigenesis in a MYCN mouse model of neuroblastoma (TH-MYCN), in which MYCN was constitutively expressed under the control of the rat tyrosine hydroxylase promoter." (PMID 34069817, 2021). "Here, we have described a mechanism for MYCN degradation in MYCN-dependent neuroblastoma, regulated by the ALYREF-USP3 signal." (PMID 33767157, 2021). "In our current study, we investigated the therapeutic potential of small molecule inducers of TRAIL, ONC201, and ONC206 in MYCN-amplified IMR-32 and non-MYCN-amplified SK-N-SH human neuroblastoma cell lines." (PMID 34422720, 2021). "The relationship between BRCA1, transcription regulation, and R-loops has been studied in more detail in MYCN-amplified human neuroblastoma cells." (PMID 33755171, 2021). "MYCN is also involved in metabolic reprogramming of neuroblastoma cells by enhancing glycolytic metabolism." (PMID 34847775, 2021). "Here we show that inhibition of fatty acid synthesis led to increased neural differentiation and reduced tumor burden in neuroblastoma xenograft experiments independently of MYCN-status." (PMID 33659885, 2021). "Depending on the stage, age, histological category, grade of tumor differentiation, status of the MYCN oncogene, chromosome 11q status, and DNA ploidy, NB can be categorized as low-, intermediate-, or high-risk according to the International Neuroblastoma Risk Group (INRG)." (PMID 34445807, 2021). "For example, in each neuroblastoma tumour sample, a mutation was present in only one out of five putative driver genes—ALK, ATRX, PTPN11, MYCN or NRAS." (PMID 34434669, 2021). "MYCN is a transcription factor that binds to the promoters of genes critically involved in neuroblastoma oncogenesis." (PMID 33968920, 2021). "We performed chromatin immunoprecipitation sequencing (ChIP-seq) for H3K27ac and H3K27me3 in MYCN-amplified neuroblastoma cells treated with DMSO or ATRA for 12 days and examined changes in the cis-regulatory regions associated with highly expressed genes." (PMID 34669465, 2021). "In a MYCN-amplified neuroblastoma PDX model, rigosertib delayed tumor growth and prolonged mouse survival." (PMID 34118691, 2021). "Our data demonstrate that DDX21 and CEP55 are valid therapeutic targets for the treatment of MYCN‐amplified neuroblastoma." (PMID 33497018, 2021). "In some tumor cells, MYCN oncogene is amplified, which increases RS levels, and is considered a bad prognosis in neuroblastoma." (PMID 34201502, 2021). "In sum, the presented analyses provided further evidence that MYCN-regulatory miRNAs, most prominently the miR-17-92 cluster, are enriched in MNA neuroblastoma suggesting mechanisms that limit MYCN downregulation by miRNAs in this diseases subtype." (PMID 34026620, 2021).
neuroblastoma (continued). "ALYREF contributed to neuroblastoma cell proliferation by blocking MYCN degradation through direct transcriptional upregulation of USP3, a deubiquitinating enzyme." (PMID 33767157, 2021). "The consequent increase in MYCN protein stability is an important oncogenic driver in neuroblastoma cells." (PMID 33658627, 2021). "On the other hand, suppression of miR-17-5p attenuates the proliferation of MYCN-amplified neuroblastoma cells via up-regulation of p21 and BIM." (PMID 33718173, 2021). "Altogether, the generated transcriptome dataset accurately recapitulates gene expression patterns of human MYCN-driven neuroblastoma while allowing selecting novel target genes for future functional studies." (PMID 34638267, 2021). "Here, we present long-term outcomes of the Austrian neuroblastoma trial A-NB94, initiated in 1994 to apply a risk-adapted strategy of treatment (RAST) based on age (≤/>12 months), INSS stage and MYCN Status." (PMID 33540616, 2021). "We reveal that MYCN amplified neuroblastoma cells are exquisitely sensitive to pharmaceutically induced epigenetic perturbations, with inhibition of numerous epigenetic mechanisms resulting in extensive loss of cell viability." (PMID 33968920, 2021). "MYCN amplification drives neuroblastoma cell proliferation and promotes an undifferentiated neuroblastoma phenotype, which strongly correlates with worse prognosis." (PMID 34885007, 2021). "In MYCN-amplified neuroblastoma cells, S- and G2-phase-dependent transcription is safeguarded by the MYCN-dependent recruitment of USP11 and BRCA1." (PMID 34201047, 2021). "We evaluated long-term outcome and genomic profiles in the Austrian Neuroblastoma Trial A-NB94 which applied a risk-adapted strategy of treatment (RAST) using stage, age and MYCN amplification (MNA) status for stratification." (PMID 33540616, 2021). "According to the International Neuroblastoma Risk Group (INRG) classification scheme, NB is classified as low, medium and high risk based on MYCN amplification status, metastasis, and whether the patient is older than 18 months." (PMID 34790130, 2021). "We now report that murine 9464D neuroblastoma cells, which express high levels of exogenous MYCN, grow slower in syngeneic p50(f/f);Lys‐Cre mice that lack p50 in macrophages and neutrophils, compared with p50(f/f) littermates." (PMID 33480449, 2021). "Here, we identified a novel small molecule, SE486-11, from a random drug library screen which enhanced the cytopathic effects of SAHA across a panel of neuroblastoma cell lines and completely blocked tumour growth in MYCN transgenic mice and zebrafish." (PMID 33658627, 2021). "Gene expression levels for the adrenergic neuroblastoma CRC members—MYCN, HAND2, ISL1, PHOX2B, GATA3, ASCL1, and TBX2—were assayed by quantitative RT-PCR at 1, 3, and 6 days after treatment with 5 μM ATRA." (PMID 34669465, 2021). "Over-expression of miR-17-5p has also been verified in primary neuroblastoma patients especially those with MYCN amplification and poor clinical outcome." (PMID 33718173, 2021). "MYCN expression and function in modulating gene synthesis in neuroblastoma is controlled at virtually every level, including poorly understood regulation at the post-transcriptional level." (PMID 34026620, 2021). "Treatment with SAHA and SE486-11 increased MYCN ubiquitination and degradation, and markedly inhibited tumorigenesis in neuroblastoma xenografts, and, MYCN transgenic zebrafish and mice." (PMID 33658627, 2021). "Along with age at diagnosis, histology status, and chromosomal aberrations (1p and/or 11q deletion), MYCN amplification ranks as one of the most important prognostic factors in neuroblastoma." (PMID 35008802, 2021). "Neuroblastoma cells receiving EVs produced by MYCN-activated cells were stronger inducers of cell proliferation and metabolism compared to EVs produced by MYCN non-expressing cells." (PMID 34847775, 2021).
neuroblastoma (continued). "Rigosertib delayed tumor growth and prolonged survival of mice carrying neuroblastoma MYCN-amplified PDX tumors (median survival: 31 days, treated; 22 days, vehicle) accompanied with increased apoptosis in treated tumors." (PMID 34118691, 2021). "m6A modification in the 3′UTR of MYCN promotes its interaction with miR-98, decreasing MYCN expression and inhibiting neuroblastoma progression." (PMID 34113622, 2021). "Amplification of the MYCN is a critical prognostic factor in neuroblastoma, while high expression levels of N-Myc protein have been involved in resistance to anticancer treatments." (PMID 33430027, 2021). "We therefore extended our study to include CHLA-20 human neuroblastoma cells, which are non-MYCN amplified." (PMID 34011385, 2021). "This transgenic mouse overexpresses MYCN through a tyrosine hydroxylase promoter (TH-MYCN) and was the first model used to demonstrate that MYCN amplification can drive neuroblastoma development, highlighting the MYCN pathway as a potential therapeutic target." (PMID 34327198, 2021). "MYCN gene amplification leads to overexpression of N‐Myc oncoprotein and neuroblastoma tumorigenesis." (PMID 33497018, 2021). "In a previous report of our laboratory, phenotyping of MYCN-amplified Kelly and SK-N-BE-2-C neuroblastoma cell lines, a high expression variance of metallothionein genes, such as MT2A and MT1X, was already reported, especially in Kelly cells." (PMID 34066513, 2021). "High mRNA expression of USP5 had a strong association with poor neuroblastoma patient prognosis in publicly available R2 gene expression datasets (n = 469 for Kocak dataset and n = 498 for SEQC dataset) for the MYCN-amplified patient subsets." (PMID 33658627, 2021). "Using a faithful zebrafish model of MYCN-driven neuroblastoma (dbh:MYCN), we tested the ability of isotretinoin to inhibit neuroblastoma tumor initiation and progression in vivo." (PMID 34669465, 2021). "Previous literatures have shown that MYCN amplification usually occurs in about 20% of neuroblastoma." (PMID 34109133, 2021). "Using a switchable MYCN system coupled to mass spectrometry analysis, we found that MYCN regulates distinct sets of proteins in the EVs secreted by neuroblastoma cells." (PMID 34847775, 2021). "We previously reported that MondoA knockdown in MYCN-driven neuroblastoma cells leads to induction of apoptosis due, at least in part, to decreased FASN (fatty acid synthase) expression and attenuated fatty acid biosynthesis." (PMID 34669700, 2021). "Treatment of MYCN-amplified neuroblastoma mouse models with mirin resulted in a significant reduction in tumor growth." (PMID 33498525, 2021). "ChIP-seq for MYCN was also performed across several MYCN-amplified neuroblastoma lines to generate a consensus map of around 10,000 regions that exhibited strong MYCN occupancy." (PMID 34200747, 2021). "The best known example is the compound 10058-F4, a c-Myc inhibitor that also prevented MYCN/MAX hetero-dimerization in vitro, inhibited tumour growth and improved survival in a MYCN transgenic mouse model of neuroblastoma." (PMID 34064704, 2021). "In MYCN-amplified neuroblastomas, WDR5 functions as a core cofactor participating in transcriptional activation and tumorigenesis under the guidance of N-Myc." (PMID 34658888, 2021). "The molecular and genetic features of neuroblastoma, such as MYCN amplification and stemness status, have established themselves not only as potent prognostic and predictive factors but also as intriguing targets for personalized therapy." (PMID 35008802, 2021). "Our results suggest USP5 protects MYCN protein from ubiquitin-mediated degradation by lowering unanchored polyubiquitin chain levels in neuroblastoma cells, an effect which can be reversed by direct binding of both drugs to USP5." (PMID 33658627, 2021).
neuroblastoma (continued). "NTRK1/TrkA expression and MYCN amplification are hallmarks of excellent and dismal outcome, respectively, in childhood neuroblastomas (NBs)." (PMID 34771457, 2021). "In vivo studies have demonstrated the efficacy of miRNA antagonism in suppression of proliferation of MYCN-amplified neuroblastoma cells in animal models." (PMID 33718173, 2021). "Taken together, genetic and pharmacologic inhibition of KDM6B predominantly leads to downregulation of the pRB-E2F transcriptional program, particularly in MYCN-amplified neuroblastoma cells." (PMID 34893606, 2021). "CBP/p300 inhibition shows potential as a therapeutic approach for advanced drug resistant MYCN amplified metastatic neuroblastoma tumours." (PMID 33968920, 2021). "In support of an oncogenic role for TERT, neuroblastoma cell lines having rearrangements or MYCN amplification exhibited both upregulated TERT expression and enzymatic telomerase activity." (PMID 34796286, 2021). "GLDC expression is markedly increased in MYCN-amplified neuroblastomas, which is required for neuroblastoma cell proliferation and tumorigenicity." (PMID 34244482, 2021). "In recent work, we have shown that NCT-503 reduces proliferation in vitro and initial tumour growth in vivo in MYCN-amplified neuroblastoma cells." (PMID 34192988, 2021). "Anti-tumour activity is evident in preclinical models of acute T-cell leukaemia, multiple myeloma, MYCN-amplified neuroblastoma, small cell lung cancer, triple-negative breast cancer and colorectal cancer." (PMID 34344865, 2021). "Using a similar approach, we found that spliceosome assembly was the most enriched pathway in neuroblastomas with MYCN amplification." (PMID 34788094, 2021). "We found USP5 was located in both the nucleus and cytoplasm of MYCN-amplified neuroblastoma cells lines, whereas MYCN was predominantly located in the nucleus." (PMID 33658627, 2021). "Here, we obtained the proteomic profiles of an MYCN-amplified neuroblastoma cell line upon ectopic NTRK1 expression and activation." (PMID 34771457, 2021). "Taken together, SMARC inhibition provides a promising future therapeutic direction for relapsed MYCN amplified neuroblastoma." (PMID 33968920, 2021). "Nevertheless, the impact of KDM6B inhibition on E2F pathways was more dramatic in MYCN-amplified neuroblastoma cells." (PMID 34893606, 2021). "Mechanistic experiments revealed that MYCN was dependent on ALYREF to drive neuroblastoma cell proliferation and the two proteins acted in a positive interconnected regulatory pathway that was essential for sustaining mutual, oncogenic expression levels." (PMID 33767157, 2021). "Some MYCN-targeting miRNAs are downregulated in neuroblastoma like for instance members of the let-7 family." (PMID 34026620, 2021). "One explanation for these findings is the difference in MYCN amplification in the two cell lines, which is related with a more aggressive phenotype in neuroblastoma." (PMID 34206917, 2021). "Genome‐wide differential gene expression studies identified centrosomal protein CEP55 as one of the genes most dramatically downregulated after DDX21 knockdown in MYCN‐amplified neuroblastoma cells." (PMID 33497018, 2021). "We and others have shown that increased MYCN protein stability is acquired by neuroblastoma cells, even in the presence of MYCN amplification, by multiple feed-forward expression loops involving MYCN trans-activation and -repression target genes." (PMID 33658627, 2021). "Cellular dependency on the ATR-CHK1 pathway is identified as a synthetic lethal interaction with oncogene-induced RS, with clinical application expected for MYCN-amplified neuroblastomas." (PMID 34069817, 2021).